KYAT1 (kynurenine aminotransferase 1)
Description:
Catalyzes the irreversible transamination of the L-tryptophan metabolite L-kynurenine to form kynurenic acid (KA), an intermediate in the tryptophan catabolic pathway which is also a broad spectrum antagonist of the three ionotropic excitatory amino acid receptors among others. Also metabolizes the cysteine conjugates of certain halogenated alkenes and alkanes to form reactive metabolites. Catalyzes the beta-elimination of S-conjugates and Se-conjugates of L-(seleno)cysteine, resulting in the cleavage of the C-S or C-Se bond.
Synonyms: GTK; KATI; CCBL1; KAT1
Tractability: Small molecule: a structure with a bound ligand is known; it has a high-quality binding pocket. PROTAC: ubiquitination databases record sites on it; a small molecule that binds it is known.
Target class: Enzyme
Gene: Protein-coding gene on chromosome 9 (128,832,937 to 128,882,556, reverse strand). Ensembl gene ENSG00000171097.
Subcellular location: Cytoplasm, cytosol
Subcellular location (Human Protein Atlas): Cytosol
Pathways (Reactome):
Metabolism: Glutamate and glutamine metabolism; Phenylalanine metabolism; Tryptophan catabolism
Gene Ontology:
Molecular function: cysteine-S-conjugate beta-lyase activity; glutamine-phenylpyruvate transaminase activity; kynurenine-oxoglutarate transaminase activity; protein binding; protein homodimerization activity; pyridoxal phosphate binding
Cellular component: cytosol; mitochondrion
Genetic constraint (gnomAD): Loss-of-function variants: 47 observed, 55.74 expected, observed/expected ratio (o/e) 0.84, 90% interval 0.67 to 1.08. The upper end of that interval is the gene's LOEUF score, 1.08, which puts it in group 4 of 6, group 1 being the genes least tolerant of losing a copy. Missense variants: 480 observed, 582.89 expected, observed/expected ratio (o/e) 0.82, 90% interval 0.76 to 0.89. Synonymous variants: 212 observed, 217.93 expected, observed/expected ratio (o/e) 0.97, 90% interval 0.87 to 1.09.
Homologues: Orthologues: chimpanzee KYAT1 (99% identical), macaque KYAT1 (96% identical), pig KYAT1 (88% identical), dog KYAT1 (86% identical), guinea pig KYAT1 (82% identical), rat Kyat1 (82% identical), mouse Kyat1 (82% identical), tropical clawed frog kyat1 (60% identical), zebrafish kyat1 (60% identical), Caenorhabditis elegans nkat-3 (40% identical), Caenorhabditis elegans nkat-1 (38% identical), Drosophila melanogaster CG1640 (19% identical), and 2 more. Paralogues in human: KYAT3 (51% identical), GPT (21% identical), GPT2 (20% identical), TAT (18% identical), ACCS (17% identical), ACCSL (16% identical), AADAT (14% identical).
Diseases named in the same sentence as KYAT1 in open-access papers:
KYAT1 is named in the same sentence as 28 diseases in open-access papers, as found by Europe PMC text mining. Sharing a sentence is not in itself a finding about the gene and the disease. The quoted sentences say what the papers report.
schizophrenia (4 papers, 2016 to 2024). A major psychotic disorder characterized by abnormalities in the perception or expression of reality. "Kynurenine aminotransferase 1 is known to be involved in tryptophan metabolism (DBGET: T01001, hsa00380), where it converts kynurenine, an intermediate of the tryptophan degradation pathway, into kynurenic acid, a neurotoxic compound associated with schizophrenia." (PMID 27884205, 2016).
depression (3 papers, 2021 to 2024). "The results indicated that Atp6v1f, Arpc5, Adcyap1r1, Ndufb6, and Psmc6 were distinctly dysregulated in the hypothalamus of the depression-susceptible group, while Gys1, Pgp, Klc1, Chka, Ncstn, Ndufa6, and Kyat1 were distinctly dysregulated in the anxiety-susceptible group." (PMID 33737865, 2021).
hepatocellular carcinoma (2 papers, 2021 to 2026). A malignant tumor that arises from hepatocytes. "Our previous work has demonstrated the utility of mRNA-based KYAT1 delivery in hepatocellular carcinoma models." (PMID 41412036, 2026).
liver cancer (2 papers, 2023 to 2026). An epithelial or non-epithelial malignant neoplasm that arises from the liver. "This study demonstrates that structure-guided mutagenesis of human KYAT1 significantly alters its catalytic profile toward MSC, enhancing its therapeutic potential in liver cancer cells, and possibly other cancer models." (PMID 41412036, 2026).
Stroke (2 papers, 2021 to 2023). Sudden impairment of blood flow to a part of the brain due to occlusion or rupture of an artery to the brain. "Furthermore, we examined the mRNA levels of TPH1, IDO1 and KYAT1 genes in peripheral venous blood with the aim of assessing (i) whether there are changes in their expression during the course of stroke and (ii) does any of their investigated SNPs have an impact on gene expression." (PMID 34680558, 2021).
Anxiety (1 paper, 2021). Intense feelings of nervousness, tension, or panic often arise in response to interpersonal stresses. "It was observed that the expressions of Gys1, Chka, Ncstn, and Ndufa6 were significantly down-regulated whereas Pgp, Klc1, and Kyat1 were up-regulated in the anxiety-susceptible group as compared to the control group." (PMID 33737865, 2021).
COVID-19 (1 paper, 2022). A disease caused by infection with severe acute respiratory syndrome coronavirus 2. "In random forest models for COVID-19, CST5, DPP7, NADK, KYAT1 and TYMP showed the highest variable importance." (PMID 35967328, 2022).
ischemic stroke (1 paper, 2021). A stroke disorder caused by obstruction of blood flow to the brain, due to thrombotic (local blood clot formation) or embolic (due to a blood clot or other material traveling from another site) event. "We present data demonstrating associations between ischemic stroke and variants of four genes (TPH1, IDO1, KYAT1 and AADAT) encoding enzymes of Trp metabolism." (PMID 34680558, 2021). "Furthermore, we also wished to learn whether changes are detectable in the expression of TPH1, TPH2, IDO1, KYAT1 and AADAT genes in peripheral blood samples (PBS) of ischemic stroke patients during the course of the disease." (PMID 34680558, 2021).
steatosis (1 paper, 2024). Increased lipid within the cytoplasm of cells. "Individuals with PWS and steatosis revealed elevated levels of the KYAT1 gene compared with those without the condition." (PMID 39336733, 2024).
cancer (6 papers, 2019 to 2026). A tumor composed of atypical neoplastic, often pleomorphic cells that invade other tissues. "MicroRNA-guided tumor-specific induction of KYAT1 combined with the MSC has great potential in treating cancers beyond cure." (PMID 37342563, 2023). "MicroRNA-guided tumor-specific induction of KYAT1 in combination with the non-toxic prodrug (MSC) has a great potential in the treatment of cancers that are currently beyond cure such as HCC." (PMID 34356326, 2021).
tumor (4 papers, 2020 to 2023). "We present herein a novel strategy to achieve efficient and specific tumoricidal effects by combining the prodrug MSC with tumor-specific microRNA-guided overexpression of KYAT1." (PMID 34356326, 2021). "KYAT1 expression was significantly reduced in cells with high levels of miR122 supporting the concept of miR-guided induction of tumor-specific cytotoxicity." (PMID 34356326, 2021). "Hence, the selective induction of KYAT1 in tumor cells in the presence of MSC may represent an attractive route to selectively induce cytotoxicity in tumor cells." (PMID 34356326, 2021). "Thus, the β-elimination activity of KYAT1 could be a valuable biomarker for determining which tumor would respond to MSC treatment." (PMID 32033380, 2020). "Both metabolites of MSC by KYAT1, i.e., MS and MSP, possess anti-tumor and anti-proliferative properties." (PMID 32033380, 2020). "Several publications have shown the anti-tumor and chemo-preventive effects of MSC metabolites produced by KYAT1, metabolites such as methylselenol and β-methylselenopyruvate (MSP)." (PMID 32033380, 2020).
cardiovascular diseases (1 paper, 2022). "On the contrary, FAM72A, KYAT1, LRRC38, and PTCHD4 had little or no known associations with cardiovascular diseases so far although they are moderately expressed in the heart and may have unidentified functions in AF." (PMID 36078037, 2022).
KYAT1 also shares sentences with these, for which no sentence is quoted: AIDS dementia complex (1 paper); allergic asthma (1); Alzheimer disease (1); amyotrophic lateral sclerosis (1); bladder cancers (1); Cirrhosis (1); cognitive deficits (1); colorectal cancer (1); glioma (1); Huntington disease (1); liver diseases (1); liver steatosis (1); malaria (1); melanoma (1); meningitis (1); neurologic disorders (1).